MEG3 (maternally expressed 3)
Diseases named in the same sentence as MEG3 in open-access papers (continued):
Sharing a sentence is not in itself a finding about the gene and the disease.
tumor (continued). "In addition, many famous lncRNAs have been found to involve in gastric tumorigenesis and progression, such as HOTAIR, H19, MEG3, HOXAAS2 and KRT7-AS, also have functions in another type of tumor." (PMID 27637083, 2016). "For instance, tumor suppressors GAS5 and MEG-3 were downregulated by less than 2-fold in tumors." (PMID 27323410, 2016). "Although no direct evidence focusing on the involvement of MEG3 in cerebral ischemic injury, it was genetic phenotype silenced in brain disease and has been recognized as a novel potentially tumor-suppressing RNA in meningioma and glioma cell." (PMID 27642276, 2016). "Maternally expressed gene 3 (MEG3), GAS6-AS1 (growth-arrest-specific gene 6 antisense 1 RNA) and BANCR (BRAF activated non-coding RNA) are tumour-suppressor lncRNAs, whose down-regulation may promote the development of NSCLC." (PMID 25297942, 2014). "According to the median ratio of relative MEG3 expression (0.27) in tumor tissues, the 44 NSCLC patients were classified into two groups: High-MEG3 group (n = 21, MEG3 expression ratio ≥ mean ratio) and Low-MEG3 group (n = 21, MEG3 expression ratio ≤ mean ratio)." (PMID 24098911, 2013). "Meg3 (maternally expressed gene 3) is an imprinted long non-coding RNA that acts as a tumor suppressor." (PMID 22666422, 2012). "While TDRG1 promotes tumor progression and immune evasion by upregulating VEGF-A levels, thereby potentially contributing to endothelial anergy and impaired immune cell infiltration, MEG3 acts as a tumor suppressor by repressing VEGF expression under stress conditions such as hyperglycemia." (PMID 40429961, 2025). "Additionally, the expression of POU3F3 and MEG3 correlate in tumour tissue but not in normal tissue, pointing towards some undiscovered pathological mediators between POU3F3 and MEG3." (PMID 41463281, 2025). "Interestingly, serum MEG3 expression level showed a negative correlation with tumor stage in the current study." (PMID 38704452, 2024). "The findings from the global demethylation assay further support the notion that hypermethylation of MEG3-DMR CGIs could, at least in part, influence the region’s expression, as evidenced by the restored expression of these lncRNAs in tumor cell lines post-treatment." (PMID 38920632, 2024). "Moreover, MEG3 indicated notably reduced expression in NPC tissues with III + IV clinical stage, T3 + T4 local tumor invasion, and N2 + N3 lymph node status than those with I + II clinical stage, T1 + T2 local tumor invasion, and N0 + N1 lymph node status (all p < 0.05)." (PMID 39049088, 2024). "Additionally, an increase in apoptotic marker “caspase 3” and a decrease in tumor marker “MKI67” were detected after the expression of lncRNA MEG3 with or without HCV core protein (C191)." (PMID 36005145, 2022). "Moreover, MEG3 (maternally expressed gene 3), which is expressed at a low level in ESCC, has been reported to inhibit the proliferation, migration, and apoptosis of ESCC cells in vitro and tumor development in vivo." (PMID 35903713, 2022).
tumor (continued). "Therefore, the MEG3/NLRP3/caspase-1/GSDMD pathway may be one of the important mechanisms for DDP to induce pyroptosis and exert anti-tumor effects in TNBC." (PMID 34326697, 2021). "Compared with normal tissue, MEG3 expression is also significantly reduced or absent in meningiomas, epithelial ovarian cancer, and squamous cell carcinoma of the tongue, supporting its role as a tumor suppressor." (PMID 33722609, 2021). "Of note, no MEG3 downregulation or H19 upregulation was observed in tumor lesions." (PMID 33030666, 2021). "In the present research, we determined that MEG3 was expressed at a low level in clinical MEN specimens and cell lines (IOMM-Lee and CH157-MN) with respect to the matched controls, indicating the possible tumor-suppressive role of MEG3 in aggressive phenotypes." (PMID 33251130, 2020). "With the rise of studies on the functional properties of lncRNAs, it has been verified that lncRNAs can efficiently affect the biological processes of cancers, some of which may serve as tumor or metastasis inhibitors, such as GAS5 and MEG3, while others may promote oncogenesis, such as SChLAP1." (PMID 32694942, 2020). "Unlike MALAT1 and H19, MEG3 usually plays the role of a tumor suppressor." (PMID 33520725, 2020). "Thirdly, animal models were not established to verify whether methylated MEG3 might depress tumor growth." (PMID 32618397, 2020). "In addition, maternally expressed genes 3 (MEG3), GAS6-AS1, BANCR are tumor suppressor lncRNAs, and their down-regulation may promote the initiation and development of NSCLC." (PMID 30840927, 2019). "However, MEG3 plus β-catenin did not significantly alter the xenograft tumor appearance time (9.08 ± 1.62 days versus 9.4 ± 2.37 days, n = 6, P = 0.41429 >0.05)." (PMID 29449541, 2018). "However, MEG3 plus β-catenin did not significantly alter the xenograft tumor weight (0.4767 ± 0.1138 g versus 0.4533 ± 0.089 g, n = 6, P = 0.251967 >0.01)." (PMID 29449541, 2018). "On the other hand, MEG3 knock-out promotes the expression of VEGF (vascular endothelial growth factor) signaling pathway genes in the brain, suggesting that MEG3 function as tumor suppressor may in part be due to angiogenesis inhibition." (PMID 29165379, 2017). "This vector was found to be fast, effective and safe for the targeted delivery of lncRNA MEG3 RNA to the epidermal growth factor receptor (EGFR)-positive HCC cell lines without the activation of EGFR downstream pathways, and significantly attenuated both in vitro and in vivo tumor cell growth." (PMID 26992211, 2016). "Tumor growth in the GE11-VLPs-MEG3 group was significantly slower than that in the GE11-VLPs-NC and PBS groups, indicating that GE11-VLPs-MEG3 could significantly inhibit tumor growth in vivo." (PMID 26992211, 2016). "However, MEG3 expression was not correlated with histological subtype, patient age, gender, or tumor position." (PMID 24098911, 2013). "Meg3 is essential for embryonic development indicated by the premature lethality of Meg3 knockout mice; therefore, the role of Meg3 in tumor development could not be assessed in mouse models." (PMID 22666422, 2012). "For instance, silencing lncRNAs such as MEG3, FTX, and MIAT in tumor-infiltrating myeloid or T cells, or enhancing expression of pro-inflammatory lncRNAs like NEAT1 or MIR17HG in T cells, may reduce immunosuppression, promote infiltration, and enhance activation of anti-tumor immunity." (PMID 40527978, 2025). "Thus, it appears that in metastatic cells that have separated from the primary tumor and migrated into the abdominal cavity, a partial transition of EMT occurs, which is accompanied by a decrease in the methylation level of five lncRNA genes: HAND2-AS1, KCNK15-AS1, MEG3, SEMA3B-AS1, and ZNF667-AS1." (PMID 39519394, 2024). "The expression of MEG3 in the tumor cells could not be restored by 5-Aza-dC therapy alone." (PMID 38920632, 2024).
tumor (continued). "Similarly, a previous study investigating the relation between mir-141 and MEG3 in GC tissues in comparison with adjacent non-tumor tissues has demonstrated no significant changes in MEG3 expression in H. pylori positive samples compared to H. pylori negative samples (P > 0.05)." (PMID 35186192, 2022). "In addition, MEG3 may activate RB1 directly by RNA–protein interactions or indirectly by activating CDKN4A, which in turn activates the RB1 to suppress cell proliferation and tumor formation." (PMID 29069869, 2017). "Unlike SARCC, MEG3 has a broader impact on signaling and apoptosis pathways, indicating a more extensive role in RCC tumor suppression." (PMID 40242248, 2025). "Significant correlations were recorded between MEG3 and anatomical site, SIRT1 and tumor stage, and miR-27a/IGFBP3 and LN metastasis among obese CRC patients, while IGF1 was correlated with tumor stage and LN metastasis among non-obese CRC patients." (PMID 38704452, 2024). "Neuron functional genes such as CaMK2N1, MEG3, SNCB, SYT1, DKK3 are almost expressed in the marginal area of the tumor (not shown)." (PMID 39257581, 2024). "Expression of MEG3 and HOTAIR lncRNAs was quantified by qRT-PCR and compared between tumor and non-tumor tissues." (PMID 35186192, 2022). "The ROC curve analysis revealed that the expression levels of MEG3 and HOTAIR might discriminate GC tumor and non-tumor tissues." (PMID 35186192, 2022). "Furthermore, sensitivity and specificity of the MEG3 and HOTAIR expression levels for discrimination of the tumor and non-tumor samples were evaluated by Receiver operating characteristic (ROC) curve analysis." (PMID 35186192, 2022). "Other oncogenic and tumor suppressor lncRNAs such as TUS7 S and MEG3 were also not detected." (PMID 34571795, 2021). "Indeed, the combination of HDAC3 inhibitor RGFP966 with a DNA demethylation reagent, 5-aza-2-deoxycytidine, synergistically enhanced the expression of several tumor suppressors such as p16, PTEN, STAT1, CD40, and large non-coding RNA MEG3, accompanied by growth suppression." (PMID 35646715, 2022). "Besides, they demonstrated the negative expression of MEG3 with TNM stage and tumor size." (PMID 35186192, 2022). "H19 and Meg3 are upregulated during the transition in vitro to in vivo in the presence of KSHV (KSHV (+) tumors versus KSHV (+) cells), but in this same transition in the absence of KSHV these lncRNAs are not upregulated (KSHV (−) tumors versus KSHV (−) tumor cells)." (PMID 34222014, 2021). "However, whether MEG3/NLRP3 axis induces pyroptosis of TNBC and whether it mediates the anti-tumor effect of DDP in TNBC has not been reported yet." (PMID 34326697, 2021).
cancer (368 papers, 2005 to 2026). A tumor composed of atypical neoplastic, often pleomorphic cells that invade other tissues. "Aberrant expression of MEG3 has been implicated in several cancers, including genitourinary malignancies." (PMID 40242248, 2025). "The unique nature of lncRNAs, including their high specificity, and sensitivity in detecting cancer, makes MEG3 a promising diagnostic biomarker." (PMID 40242248, 2025). "Some studies have indicated the association of HOTTIP and MEG3 genetic polymorphisms with cancer susceptibility." (PMID 39049088, 2024). "Of the IGHV-associated miRNAs, (14/38 (37%)) derived from chr14q32 clusters where all miRNAs were co-expressed with the MEG3 lncRNA from a cancer associated imprinted locus." (PMID 37169950, 2023). "According to one study, MEG3 expression was reduced in cervical tissues, and it was associated with cancer size, lymph node metastasis, high-risk HPV infection, and the FIGO stage." (PMID 37007117, 2023). "Reduced expression of MEG3, which inhibits cancer cell proliferation, migration, and invasion and promotes apoptosis, has been linked to cancer development and progression." (PMID 37007117, 2023). "The most significantly downregulated gene was MEG3, which is a long non-coding RNA previously implicated in Alzheimer’s pathology and in several cancers." (PMID 36012404, 2022). "Several lines of evidence also suggest that the inactivation of this gene and the subsequent loss of the MEG3 lncRNA (along with its diseases-suppressive properties) are frequently documented in numerous cancers and diabetic environments." (PMID 35464068, 2022). "In this review, we summarized the current knowledge regarding the expression level, functions, as well as the molecular mechanism underlying MEG3 regulation on cancer hallmarks." (PMID 36551518, 2022). "The lost or reduced expression of MEG3 in different cancers has been associated with promoter hypermethylation and hypermethylation of the intergenic region." (PMID 35755302, 2022). "Cancer-associated fibroblasts were strongly associated with MEG3 expression across all four deconvolution algorithms that can measure this cell type." (PMID 36231143, 2022). "Recent studies revealed that MEG3 is associated with hallmarks of cancer, including proliferation, cell death, invasion and metastasis, metabolic reprogramming, and angiogenesis, by regulating various pathways." (PMID 36551518, 2022). "Some polymorphisms in lncRNA maternally expressed gene 3 (MEG3) are considered as well-established cancer biomarkers and therapeutic targets due to their association with cancer risk and response to chemotherapy." (PMID 34199840, 2021). "MEG3 is an imprinted gene located at 14 q32, which encodes a lncRNA associated with multiple human cancers." (PMID 33446761, 2021). "LncRNAs like MALAT1 and HOTAIR which are associated with metastasis are over expressed in cancer and MEG3 and PTENP1 which inhibit cell proliferation and migration are downregulated in cancer." (PMID 34858475, 2021). "SNPs in MEG3 have been related to cell phenotypes, increased cancer risk, and chemotherapy toxicity in other cancers." (PMID 34421993, 2021). "A loss of MEG3 expression has been found across human cancer cell lines, and decreased MEG3 levels significantly correlate with TNM stage, lymph node metastasis and differentiation grade." (PMID 34527584, 2021). "Although the association of MEG3 gene rs7158663 polymorphism with cancer susceptibility has been investigated, the findings are inconsistent." (PMID 34956908, 2021). "MEG3, located on chromosome 14q32.3, has been associated with various tumors and regarded as a putative cancer biomarker and treatment target." (PMID 33932142, 2021). "We investigated the A > G RNA-editing event at 14:100846310 in the cancer-implicated lincRNA MEG3; this position was edited in 6 of the 7 samples." (PMID 34551708, 2021). "We found that lower MEG3 expression was often associated with a poorer prognosis in these cancer patients." (PMID 34220951, 2021).
cancer (continued). "In another study, MEG3 rs10132552 was reported to be associated with treatment response in cancer patients." (PMID 33119060, 2020). "EMT has been suggested to promote metastatic behavior of epithelia-originating cancer and, in addition, our data shows association of MEG3 expression with the mesenchymal phenotype." (PMID 32612992, 2020). "Meta-analysis demonstrated that low expression of MEG3 is associated with poor survival in cancer patients." (PMID 32190687, 2020). "Researchers found loss of MEG3 related to a variety of human cancers, such as gastric, cervical, and breast cancer." (PMID 32669097, 2020). "Surprisingly, in contrast with other LncRNAs, there is increasing evidence that LncRNA MEG3 is down-regulated in various types of tumors, and low levels of MEG3 are associated with poor prognosis in cancer patients." (PMID 31654067, 2019). "The lncRNA maternally expressed gene 3 (lncRNA MEG3), a tumor suppressor, has been shown to be associated with the proliferation, migration, and invasion of many cancers, like colorectal cancer, gastric cancer, prostate cancer." (PMID 30156956, 2019). "The loss of MEG3 expression caused the formation of various types of cancers, while over-expression of MEG3 inhibited them." (PMID 29449542, 2018). "Our results indicated that lower expressions of MEG3 represented a risk factor for OS in cancers (HR = 0.43, 95% CI = 0.15–1.24, P = 0.006, fixed-effect)." (PMID 28157702, 2017). "Previous studies have indicated that loss of MEG3 expression in cancer can result from hypermethylation of the MEG3 promoter as well as the intergenic germline-derived differentially methylated region." (PMID 28407691, 2017). "Studies have demonstrated that MEG3 is associated with cancer initiation, progression, metastasis and chemo-resistance." (PMID 29069869, 2017). "In summary, some lncRNAs like MEG3 are strongly associated with the clinicopathological outcome of various cancers." (PMID 29069869, 2017). "Several lncRNAs that were previously implicated in cancer, including MEG3, ANRIL and UCA1, are deregulated by KSHV." (PMID 28715488, 2017). "The downregulation of MEG3 is commonly associated with the progression of different types of cancer; in fact, MEG3 has the strong ability to inhibit the proliferation of several malignant human carcinoma cell lines." (PMID 29165379, 2017). "Like MEG3, the levels of these miRNAs have also been shown to affect cancer development and influence cancer cell chemosensitivity, which is directly linked to the prognostic outcome of different cancers." (PMID 29069869, 2017). "Recent meta-analysis studies also demonstrate the association of MEG3 level with cancer stages and survival outcome." (PMID 29069869, 2017). "Low expression of MEG3 is associated with an increased risk of metastasis and a poor prognosis in cancer patients." (PMID 28157702, 2017). "Many normal human tissues express MEG3 and the loss of MEG3 expression has been reported in several types of cancer." (PMID 28637507, 2017). "Among lncRNAs, we confirm previously-reported downregulation of GAS5 and MEG-3, and identify for the first time dysregulation of cancer-associated H19 and PCAT-1 in HNSCCs." (PMID 27323410, 2016). "For example, ANRIL was associated with 14 types of cancer and MEG3 was associated with 18 types of cancer." (PMID 24498199, 2014). "While MEG3 is expressed in many normal human tissues, reduced levels of MEG3 are frequently observed in a variety of cancers and associated with hyper-proliferation." (PMID 24216986, 2013). "Moreover, it has been revealed that HOTTIP up-regulation or MEG3 down-regulation is associated with cancer pathogenesis and progression." (PMID 39049088, 2024). "MEG3 is a nuclear retained lncRNA encoded by chromosome 14q32.3 with a length of 35 kb and consisting of 10 exons; loss of MEG3 has been linked to various human cancers, and several studies have uncovered the downregulation of MEG3 in MASLD mouse models." (PMID 39872125, 2024).